L1CAM (L1 cell adhesion molecule)
Diseases named in the same sentence as L1CAM in open-access papers (continued):
Sharing a sentence is not in itself a finding about the gene and the disease.
tumor (continued). "viii) A high abundance of fibroblasts (L1) in the tumoral stroma correlated with increased L1CAM expression in the carcinoma cells (P2) and high numbers of CD68+ (H1) and CD163+ (I1) macrophages correlated with elevated vimentin expression in tumor cells (R)." (PMID 24797069, 2014). "In addition, high levels of CD3 but low levels of FoxP3 and L1CAM in tumor cells tended to correlate with improved patient survival, being in line with previous reports demonstrating high tumor-associated expression of FoxP3 and L1CAM as negative prognostic marker." (PMID 24797069, 2014). "Blockade of the β3 integrin ligands L1CAM and CD31 reduced tumor cell transmigration, supporting the role of active adhesion mechanisms in tumor cell transit across lymphatic endothelial cells in our experimental conditions." (PMID 24884715, 2014). "Immunohistochemistry confirmed the presence of estrogen and progesterone receptors, as well as expression of the L1 cell adhesion molecule (L1CAM) in the endometriotic and the tumor tissue." (PMID 24371719, 2013). "In tumor cell lines, SSEA-5 was highly immunoreactive in Capan-1 cells, while L1CAM was highly immunoreactive in U87MG cells." (PMID 26317026, 2013). "In contrast to CD44, L1CAM, and CD97, transplantation of Lin-CD24+CD29+ cells revealed a slight yet significant enrichment in tumour-initiating cells (estimated frequency of 1 in 56463, with CI of 399211 to 7986)." (PMID 24069241, 2013). "This list of cell lines is not exhaustive and further investigation into the presence these markers in a variety of tumor cell types is warranted to determine the significance of SSEA-5 and L1CAM expression." (PMID 26317026, 2013). "The aim of this study was to investigate the expression of L1CAM in HCC and determine its correlation with tumor progression and prognosis." (PMID 22888955, 2012). "It has already been shown to be prognostic in retrospective cohorts of EC, especially in low-grade early-stage tumours, with patients having worse outcomes than patients without L1CAM expression." (PMID 41561510, 2025). "In vivo luciferase-expressing L1CAM-targeting CAR T cell trafficking and expansion was monitored by longitudinal bioluminescence imaging (BLI) in mice subcutaneously xenografted with either transgenic or unmodified tumour cell lines in the flank." (PMID 41366257, 2025). "Notably, TRL treatment enhanced the tumor’s response to Gemcitabine by decreasing collagen and MMP2 levels while simultaneously increasing L1CAM expression." (PMID 40770187, 2025). "Their results showed diffuse membranous L1CAM expression in all LOTs, with negative or focal non-membranous staining in the other tumor types." (PMID 40805143, 2025). "Manipulating L1CAM-CAR T cells with CRISPR/Cas9 to knock out SELPLG expression or enhance SH2D2A expression did not affect CAR T cell functions necessary for anti-tumor activity in vitro." (PMID 41394860, 2025). "L1CAM is not required for tumor initiation but is necessary for primary tumor propagation and liver metastatic colonization." (PMID 40027151, 2025). "They observed that L1CAM-specific CAR-T cells infiltrated the 3D tumor model from the top to the bottom, displaying strong activation marked by increased interferon-gamma (IFNG) release and potent tumor-killing capacity." (PMID 41488666, 2025). "In terms of therapeutic efficacy, no tumour remission was observed in mice bearing L1CAM-low (SK-N-AS) tumours, regardless of CXCL10 expression." (PMID 41366257, 2025). "From the BIOEMBRACE study, p16 negative status and tumor necrosis on MRI were independently associated with a poor response to CRT, whereas PD-L1 expression and L1CAM ≥ 50% had an independent adverse impact on local and pelvic control." (PMID 39857985, 2025).
tumor (continued). "In Van Gool's study, including high-risk patients (as handled in PORTEC-3) from the TRansPORTEC collaborating institutions, L1CAM-positive tumours (defined as >10%) did not predict prognosis, whereas an alternative threshold (>50%) did." (PMID 41561510, 2025). "Distinctively, in the eosinophilic pattern of chRCC cases, focal L1CAM positive tumor cells showed no L1NC01187 expression (mutually exclusive as in HOT)." (PMID 37994665, 2024). "Moreover, the L1CAM-specific CAR T cells were highly activated by increased interferon gamma (IFNG) release and tumor cell cytotoxicity." (PMID 38520648, 2024). "To explore if other key ALCAM-binding partners may contribute to the tumour-mesothelial interactions, we tested two well established partners, namely CD6 and L1CAM in all the cells used here." (PMID 36614319, 2023). "If no somatic alterations had significant associations the tumor response, overexpression of IGF2 and L1CAM was associated with decreased response." (PMID 36766755, 2023). "High‐grade tumours showed increased L1CAM expression (mean logRQ 6.5 vs 4.5, P = .032), as well as non‐endometrioid ECs (mean logRQ 7.5 vs 4.8, P = .001)." (PMID 35429348, 2022). "Notably, the tumor-suppressive effect of extracellular GAPDH was suppressed by silencing L1CAM in SW1353 CS cells, indicating that L1CAM in tumor cells mediated GAPDH-driven anti-tumor action." (PMID 35804814, 2022). "Unlike the previous two migratory markers, we did not see a robust overexpression of L1CAM in the tumour tissue of untreated animals (32% positivity)." (PMID 34910361, 2022). "Moreover, we found an increased accuracy (68% vs 63%) for the model including L1CAM vs a model with FIGO stage and tumour grade only, estimated via leave‐one‐out cross‐validation." (PMID 35429348, 2022). "L1CAM can also be cleaved by the metalloproteinases, ADAM10 and ADAM17, which further results in the release of a 200 kDa soluble ectodomain fulfilling diverse functions in both tumor and immune cells." (PMID 35473609, 2022). "Thus, the expression of L1CAM was determined in THP1 overexpressing and serotonin-treated tumor cells." (PMID 35473609, 2022). "IHC analysis of L1CAM-stained whole tumor slides showed ectopic lymphoid structures at the tumor invasive border and the myometrium that expressed L1CAM independent of any L1CAM expression by the tumor itself." (PMID 35296668, 2022). "A sequence of events could be envisioned where tumor-reactive T-cells release CXCL134,23, attracting CXCR5 + LT + immune cells to the perivascular space initiating L1CAM-positive perivascular cell activation and maturation to FDCs." (PMID 35296668, 2022). "L1CAM overexpression in EC tissues represents a negative prognostic marker, signaling both more aggressive behavior of the tumor and shorter survival of patients." (PMID 34203959, 2021). "On the basis of these results, L1CAM may serve as a potential therapeutic target for patients with ESCC, because it not only inhibits tumor cell growth but also diminishes Treg infiltration." (PMID 33710805, 2021). "Although L1CAM-SS-28/ζ CAR T cells demonstrated superior anti-tumor activity in vivo, tumor control was not persistent and tumors in all mice eventually relapsed." (PMID 33801448, 2021). "The 5-year DSS for patients with L1CAM positive tumours was 78% after therapy versus 38% without adjuvant treatment." (PMID 34659530, 2021). "Furthermore, CCL22 promoted Treg recruitment to the tumor site; the Tregs then secreted TGF-β, which in turn promoted L1CAM expression via Smad2/3 in a positive feedback loop." (PMID 33710805, 2021).
tumor (continued). "In contrast with previous studies suggesting a pro-metastatic role for L1CAM, this study showed that L1CAM-low PDAC cells were less differentiated and exhibited enhanced stemness phenotypes, including increased capacity for self-renewal, tumour initiation, migration and invasion and chemoresistance." (PMID 34638468, 2021). "Treating our Rag−/− model with similarly sized tumors (200–250 mm3) with the same dose of human L1CAM-specific CAR T cells (1 × 106) produced no anti-tumor effect." (PMID 33801448, 2021). "p32 mediates tumor development by regulating the migratory and invasive properties of cancer cells through various downstream signaling pathways, including p38 MAPK and GSK3/β-Catenin/L1CAM." (PMID 34711805, 2021). "Compared to that in non-treated tumours, L1CAM expression significantly increased in MDA-MB-231 tumours treated with either irradiation or Dox." (PMID 34078883, 2021). "The genetic manipulation of L1CAM in OC cells provided gain and loss-of-function models that were then employed in cell biological assays as well as in vivo tumorigenesis experiments to assess the role of L1CAM in OC cell stemness and in OCSC-driven tumor initiation." (PMID 34645505, 2021). "Soluble vascular cell adhesion molecule-1 (SVCAM-1) increases tumor resistance to gemcitabine; however, combining gemcitabine with inhibition of the adhesion molecule L1CAM (CD171) reduces VEGF expression and the number of CD31-positive vessels, resulting in a stronger anti-tumor effect." (PMID 34439378, 2021). "L1CAM-LS-28/ζ CAR T cells delayed tumor growth in one of six mice, demonstrating no significant improvement in overall survival." (PMID 33801448, 2021). "Moreover, fibroblasts expressing amyloid beta precursor protein binding family A, member 3 (MINT3) upregulate L1 cell adhesion molecule (L1CAM) which leads to ERK1/2 activation in BrCa cells through integrin α5β1, promoting tumor growth and resistance." (PMID 34201840, 2021). "Our findings provide new insight into the mechanism of immune evasion mediated by L1CAM, suggesting that targeting L1CAM-CCL22-TGF-β crosstalk between tumor cells and Tregs may offer a unique means to improve treatment of patients with ESCC." (PMID 33710805, 2021). "Moreover, it has been reported that the L1CAM intracellular domain is cleaved from the membrane-bound portion of L1CAM by ADAM10 and γ-secretase, after which it is translocated to the nucleus to regulate the expression of genes involved in tumour progression." (PMID 34078883, 2021). "Interestingly, both L1CAM-specific CAR T cell subsets infiltrated into the top (indicated by the peaks between channels) and bottom of the bioprinted 3D tumor models." (PMID 34267756, 2021). "Moreover, we reported the irradiation-induced upregulation of L1CAM in NB IMR-32 cells and specifically in the cancer-stem-like cell subpopulation within the bulk tumor." (PMID 34422720, 2021). "EGFR, VEGF-A and L1CAM were highly expressed in tumor-negative tissue, whereas αvβ6 showed heterogeneous expression in metastases." (PMID 32545676, 2020). "Robust preclinical safety testing in nonhuman primates expressing the identical CE7 L1CAM epitope in a similar normal tissue distribution to humans did not reveal any evidence for on-target, off-tumor toxicities at doses 100 times those given to humans." (PMID 34113750, 2020). "In a total of 19 studies investigated the impact of full-length L1CAM (L1CAM-FL) on tumor suppression with strategies that did not specifically address domain-specific functions of L1CAM." (PMID 31455004, 2019). "However, L1Cam, a surrogate marker for RELA fusion-gene positivity, was detected only in a subfraction of tumor cells." (PMID 31480400, 2019). "Further studies then showed that L1CAM is not restricted to the nervous system and, in particular, we reported its expression in the tumor vasculature of several cancer types, while no or very low L1CAM expression is detectable in normal vessels." (PMID 30829570, 2019).
tumor (continued). "Moreover, putative stem cell markers such as L1 cell adhesion molecule (L1CAM), nucleostemin, and nestin have been found at the leading edge of the tumor, supporting opinions that CSCs are responsible for GBM invasion." (PMID 29642503, 2018). "Mint3-mediated L1CAM expression in fibroblasts stimulated the ERK signalling pathway via integrin α5β1 in cancer cells, and promoted cancer cell proliferation in vitro and tumour growth." (PMID 28504692, 2017). "Samples with staining in less than 10% of the tumor cells, or samples with no L1CAM staining, were considered negative (N = 292, 79%)." (PMID 29152102, 2017). "However, when we focused on fibroblasts, the number of fibroblasts expressing L1CAM, Mint3 and MT1-MMP was higher in cancer regions than that in adjacent non-tumour regions." (PMID 28504692, 2017). "In so far one substantial weakness of whole tissue qRT-PCR compared to IHC, is that L1CAM mRNA expression in those small tumor cell clusters in otherwise L1CAM negative cancers can be underestimated." (PMID 27174921, 2016). "Accumulation of myofibroblasts in turn correlated with increased L1CAM expression in ductal and tumor cells supporting experimental data on the role of macrophages and myofibroblasts in the induction of EMT by upregulating vimentin and L1CAM in ductal and PDAC cells." (PMID 24797069, 2014). "In EC tumor tissues we found elevated miR-34a levels only in 3/18 endometrioid ECs that are considered type I. In these cases we noted that L1CAM negative areas expressed higher amounts of miR-34a than the respective L1CAM positive areas." (PMID 24497324, 2014). "Once tumors had developed, as demonstrated by BLI, tumor-bearing mice received liposome SN-encapsulated L1CAM siRNA, negative control siRNA, or the SN vehicle alone intratumorally twice a week for 3 weeks, or else received no treatment." (PMID 25294816, 2014). "In areas positive or negative for L1CAM within the same tumor no consistent differences were observed." (PMID 23530769, 2013). "It should be noted that the authors did not compare L1CAM positive and negative parts of the same tumor." (PMID 23530769, 2013). "Another possibility is that additional mechanisms of regulation are involved in tumor tissues and that DNA methylation is not a critical factor for dynamic expression changes of L1CAM in the tumor microenvironment." (PMID 23530769, 2013). "No striking differences in promoter methylation were observed between tumor areas with L1CAM expression and those without expression." (PMID 23530769, 2013). "The mechanism by which the L1 cell adhesion molecule contributes to tumour progression has not been clearly established." (PMID 22544341, 2013). "Therefore, we examined human tumors, tumor cell lines, teratomas, and iPSCs for immunoreactivity to SSEA-5 and L1CAM." (PMID 26317026, 2013).
tumor (continued). "We examined a variety of human tumor cell lines for SSEA-5 and L1CAM immunoreactivity." (PMID 26317026, 2013). "Nevertheless, the specific impact of alternative splicing products, including those of L1CAM, on tumour progression has not been fully elucidated so far." (PMID 21541352, 2011). "A recent study showed that L1CAM expression is preferentially higher in CD133+ GSC than in normal neural progenitors, and knockdown of L1CAM expression via shRNA interference inhibited the growth of CD133+ GSCs, disrupted sphere forming capacity, induced cell apoptosis, and suppressed tumor growth." (PMID 24212792, 2011). "This clustering supported the idea that L1CAM-CAR T cells used separate mechanisms to enter the tumor model compared to untransduced control T cells, and that non-infiltrating T cells may not be entering the tumor model for common reasons." (PMID 41394860, 2025). "Univariate regression analysis for the low‐grade group indicated that age, FIGO Stage, ER, PR, L1CAM, LVSI, tumor size, cervical stromal infiltration, pelvic lymph nodes, muscle layer infiltration, and para‐aortic lymph nodes may be important factors influencing RFS in the low‐grade group." (PMID 39996416, 2025). "We previously found that the tumor-neuroglia cell coculture did not change L1CAM mRNA expression." (PMID 40119353, 2025). "Thus, we looked for a similar phenotype in SCLC and found L1CAM positive 984 cells expressed lower levels of MHC-1 as compared to the L1CAM negative tumor cell population." (PMID 38253555, 2024). "We also observed that the VTT tissue with vessel wall invasion showed strong positive staining for L1CAM, the L1CAMhigh/CXCR2high RCCs subgroup was more prone to perivascular localization in the VTT, promoted VTT adherence to the vascular wall, and deployed the perivascular tumor niche." (PMID 37015905, 2023). "This expression of L1CAM on FDCs was independent of L1CAM overexpression by the tumor." (PMID 35296668, 2022). "None of the cases had an overall expression of L1CAM in more than 10% of the whole tumor." (PMID 35892892, 2022). "Two (4%) tumor samples were negative and one (2%) had L1CAM expression in over 90% of cells." (PMID 36142656, 2022). "By contrast, the NSMP/L1CAM-negative patients were mainly ER/PR-positive and ARID1A-negative, and showed an intermediate prognosis, likely attributable to a more favorable underlying tumor biology." (PMID 36358847, 2022). "No cases showed L1CAM positivity in ≥10% of the whole tumor." (PMID 35892892, 2022). "Previous studies from our team and others have shown that the L1 cell adhesion molecule (L1CAM) is deeply involved in the aggressive phenotype, immunosuppressive tumor microenvironment (TME), and metastasis during multiple malignancies, which may lead to an unfavorable outcome." (PMID 36387224, 2022). "Since 41% of tumours were positive for L1CAM, it cannot be ruled out as a CSC marker for OSCC." (PMID 35296132, 2022). "In addition, the relation between L1CAM serum levels and L1CAM percentage tumor positivity (if any) has not been clearly defined yet." (PMID 34203959, 2021). "Given that both L1CAM and activated STAT3 have been implicated in different tumor types, this paradigm might not be limited to OC." (PMID 34645505, 2021). "This revealed that L1CAM was co-expressed with pSTAT3 in a subpopulation of cancer cells, and the frequency of double positive cells varied greatly among samples ranging from 2 to 60% of tumor cells (data not shown)." (PMID 34645505, 2021). "L1CAM was associated with factors known to be related to a more aggressive behaviour, such as higher FIGO stage (p=0.009), non-endometrioid histology (p<0.001), high tumour grade (p<0.001), and negative ER and PR status (p<0.001)." (PMID 34659530, 2021).